TYMP (thymidine phosphorylase)
Diseases named in the same sentence as TYMP in open-access papers (continued):
Sharing a sentence is not in itself a finding about the gene and the disease.
inflammation (2 papers, 2022 to 2024). Aberrant reaction of the microcirculation characterized by movement of fluid and leukocytes from the blood into extravascular tissues. "While WD is well known to cause systemic chronic inflammation, this study is the first to demonstrate that TYMP plays an important role in WD-induced systemic inflammation." (PMID 39742002, 2024). "Sometimes such stains restricted microcirculation analysis to the glomerular compartment, especially with TYMP, in cases with severe tubulo-interstitial inflammation with de facto “uninterpretable” peritubular capillaries." (PMID 36352007, 2022).
inflammatory diseases of central nervous system (1 paper, 2022). "The 2-deoxy-D-ribose cooperates with thymidine phosphorylase and vascular endothelial growth factor to inhibit tight junction proteins, leading to the destruction of BBB, which results in inflammatory diseases of central nervous system." (PMID 35250450, 2022).
intestinal diseases (1 paper, 2025). "Given that off-target effects from target gene pleiotropy can compromise therapeutic safety, PheWAS results indicate associations between TYMP and intestinal diseases, and between GPI and corneal scars." (PMID 41142241, 2025).
neurological disease (1 paper, 2025). "Ten proteins showed co-localization with a neurological disease using both plasma protein abundance and plasma mRNA abundance (SIRPA, CTSH and CD33 with AD; and ASF1A, FCRL3, VEGFB, TYMP, PVALB, LMAN2 and CD5 with MS)." (PMID 40037332, 2025).
TYMP also shares sentences with these, for which no sentence is quoted: peripheral neuropathy (5 papers); neuropathy (3); endometrial carcinoma (2); esophageal cancer (2); heart disease (2); infection (2); lactic acidosis (2); MELAS (2); mitochondrial encephalomyopathies (2); non-small cell lung carcinoma (2); ptosis (2); Alzheimer disease (1); anemia (1); aneurysm (1); ataxia telangiectasia (1); bacterial infection (1); bone cancer (1); cardiovascular disorder (1); chronic atrial and intestinal dysrhythmia (1); deficiencies (1); ductal pancreatic adenocarcinoma (1); enteritis (1); epilepsy (1); ethylmalonic encephalopathy (1); experimental autoimmune encephalomyelitis (1); gallbladder cancer (1); gastritis (1); gastrointestinal disease (1); gastrointestinal tumor (1); Hand-foot syndrome (1).
A further 31 diseases each share a sentence with TYMP in 1 paper.